Y_RNA (Y RNA )
Gene: Miscellaneous RNA gene on chromosome 7 (73,095,357 to 73,095,458, forward strand). Ensembl gene ENSG00000199913.
Homologues: Orthologues: chimpanzee Y_RNA (99% identical), pig Y_RNA (75% identical). Paralogues in human: Y_RNA (100% identical), Y_RNA (97% identical), Y_RNA (93% identical), Y_RNA (92% identical), Y_RNA (90% identical), Y_RNA (89% identical), Y_RNA (87% identical), Y_RNA (85% identical), RNY3 (84% identical), RNY3P12 (84% identical), Y_RNA (84% identical), RNY3P1 (83% identical), and 98 more.